STAT3 (signal transducer and activator of transcription 3)
Diseases named in the same sentence as STAT3 in open-access papers (continued):
Sharing a sentence is not in itself a finding about the gene and the disease.
COVID-19 (continued). "Looking at the specific signaling map, certain molecular scenarios can be developed, where prospective HIF fluctuation in mild acute COVID-19 could be initiated by IL-6, and it may involve STAT3." (PMID 37301958, 2023). "Furthermore, STAT3 was identified to be upregulated in the context of intensive inflammation and hypoxemia, and its potential role in COVID-19 pathogenesis has been recently reviewed." (PMID 35327634, 2022). "This suggest that circulating IL-6 drives CD4 T cell STAT3 activation during acute COVID-19." (PMID 35421120, 2022). "Transcriptome studies have reported decreased levels of SOCS-3 in myeloid cells during COVID-19, which could lead to an immunosuppressive response to IL-6-mediated STAT3 activation during COVID-19." (PMID 35421120, 2022). "Therefore, licorice is proposed as an effective candidate for the treatment of COVID-19 through STAT3, IL2RA, MMP1, and CXCL8." (PMID 36120307, 2022). "In all cell populations, STAT3 was the predominant signaling pathway activated during COVID-19." (PMID 35421120, 2022). "Additionally, other groups have shown, through various techniques, the tremendous impact COVID-19 has on leukocytes and platelets in particular, including IL-6-mediated platelet activation and STAT3 phosphorylation within monocytes and T cells." (PMID 35681519, 2022). "With the potential use for COVID-19 treatment of existing drugs that enhance STAT1 or inhibit STAT3 functions, problems could arise." (PMID 35663932, 2022). "In agreement with Schulte-Schrepping’s report in which STAT3 was suspected as transcriptional factor of immunosuppressive monocytes in COVID-19, we demonstrated that immunosuppression by monocytes isolated from COVID-19 patients can be indeed reverted by STAT3 inhibitors." (PMID 34518653, 2022). "In agreement with this paradigm, a recent analysis of multi-organ proteomic landscape of COVID-19 autopsies confirmed both NF-κB and STAT3 as transcription factors largely upregulated in multiple organs, implying a widespread and pervasive activations of the two pathways." (PMID 34518653, 2022). "Indeed, JAK-STAT pathway signaling has been shown to be pivotal in developing severe symptoms such as a cytokine release syndrome in COVID-19 patients, in particular through STAT3 signaling." (PMID 35039055, 2022). "NSP1 and ORF6 from SARS-CoV-2 may impair STAT1 function in COVID-19 patients, resulting in compensatory STAT3 hyperactivation." (PMID 36059536, 2022). "In fact, STAT3 was hyperactive in saliva of COVID-19 cases suggestive of IL-19 signaling." (PMID 36163397, 2022). "Blocking of TLR4, JAK2 and STAT3 signaling could prevent excessive production of calprotectin by Dok3-/- neutrophils, revealing new targets for potential COVID-19 therapy." (PMID 36172386, 2022). "In addition, the inhibition of NFκB and STAT3 signaling pathways is considered as a promising candidate for the treatment of worsen clinical outcomes in TNBC patients with COVID-19." (PMID 35747796, 2022). "Molecular docking showed that Glycyrol, Phaseol and Glyasperin F in licorice may playe a role in treating COVID-19 by acting on STAT3, IL2RA, MMP1, and CXCL8." (PMID 36120307, 2022). "Generally, SARS-CoV-2 inhibits STAT1 and IFNs, resulting in the activation of the STAT3 pathway as a dominant signaling pathway, which could result in COVID-19 complications." (PMID 36111104, 2022). "Given that Jun, PPARG, and STAT3 are the top TFs from COVID-19 patients’ TRNs, these identified drugs may be candidates for reducing SARS-CoV-2 infection for these cell types." (PMID 35458567, 2022). "SARS-CoV-2 mediated inhibition of STAT1, and the subsequent shift to a STAT3-dominant signaling may lead to the proinflammatory conditions most commonly observed in hospitalized COVID-19 patients." (PMID 36273032, 2022).
COVID-19 (continued). "MDA5 serves as a pattern recognition receptor for SARS-CoV2 underlying the IFN response during COVID-19, and the decreased ISG expression during COVID-19 may result from increased STAT3 mediated inhibition of MDA5 activity." (PMID 35421120, 2022). "Moreover, as expected, the level of phosphorylated STAT3 (p-STAT3), which is regulated by IL-19, was significantly upregulated in saliva of COVID-19 patients compared to healthy controls, which is suggestive of IL-19 signaling." (PMID 36163397, 2022). "In previous studies, the JAKs/STAT3 for signal transduction can activate pro-inflammatory gene expressions and facilitate the NLRP3 inflammasome to secrete IL-1β and IL-18 during the pathogenesis of COVID-19-associated neurodegenerative diseases." (PMID 36698809, 2022). "Within the network, we suspected that the 6 ceRNA subnetworks (i.e., MSTRG.119845.30/hsa-miR-20a-5p/TNFRSF1B, MSTRG.119845.30/hsa-miR-29b-2-5p/FCGR2A, and MSTRG.106112.2/hsa-miR-6501-5p/STAT3) may play a crucial role in the development of COVID-19." (PMID 33833618, 2021). "Interestingly, excessive concentrations of NF-kB and STAT3 stimulators induce the lethal cytokine storm seen in COVID-19 patients." (PMID 34113349, 2021). "We then exemplify the potential clinical value of treating COVID-19 disease with STAT3 inhibitors by presenting the outcomes of two hospitalized patients with active cancer and COVID-19 receiving oral Legalon®—a nutraceutical containing the naturally occurring STAT3 inhibitor silibinin." (PMID 35056076, 2021). "COVID-19 pathophysiology is caused by a cascade of respiratory and multiorgan failures arising, at least in part, from the SARS-CoV-2-driven dysregulation of the master transcriptional factor STAT3." (PMID 35056076, 2021). "Moreover, a comparative study of COVID-19 and influenza showed the activation of STAT3/NF-κB in PBMCs of patients infected with influenza A virus (IAV)- vs. the activation of STAT1/IRF3 in COVID-19 patients." (PMID 34394120, 2021). "Importantly, a positive feedback loop of IL-6–JAK/STAT3 signaling with amplification of NF-κB activation was suggested to be involved in COVID-19 induced cytokine storm and mortality." (PMID 34639132, 2021). "This pathological phenomenon toward STAT3 may contribute to the clinical manifestations most common with COVID-19 patients in the hospital, such as coagulopathy, proinflammatory status, profibrotic condition, and T cell lymphopenia." (PMID 34177566, 2021). "If the over-stimulation of the STAT3 signaling network is a shared node of COVID-19 pathophysiology, the application of anti-STAT3 therapies to block the SARS-CoV-2 lifecycle might moderate the severity of COVID-19." (PMID 35056076, 2021). "Collectively, these data reconcile the systemic inflammatory response and functional immunosuppression induced by COVID-19 and suggest STAT3 signaling may be the central pathophysiologic mechanism driving immune dysfunction in COVID-19." (PMID 33619472, 2021). "Significantly upregulated genes were involved in “TNFα signaling via NF-κB”, “inflammatory responses”, and “cytokine-cytokine receptor interaction”, “IL6-JAK STAT3 signaling”, “coagulation”, “hypoxia”, which had been reported for COVID-19, while cell cycle-related pathways were downregulated." (PMID 34697287, 2021). "We hypothesize that IL-6-STAT3 signaling is a promising therapeutic target for the cytokine storm in COVID-19, because IL-6 is a major STAT3 stimulator, particularly during inflammation." (PMID 33014208, 2020). "Furthermore, JAK2/STAT3 signaling contributes greatly to the cytokine storm seen in severe COVID-19 via inducing the Th1/Th17 immune response, hyperactivating STAT3 while impairing STAT1 function, thereby suppressing the antivirus interferon response and coagulopathy." (PMID 39201692, 2024).
COVID-19 (continued). "The development of COVID-19-associated nephropathy (COVAN), in particular, may be mediated through IL-6 and signal transducer and activator of transcription 3 (STAT3) signaling, suggesting a direct connection between the COVID-19-related immune response and the development of chronic disease." (PMID 40012912, 2024). "Ivermectin has been shown to inhibit STAT-3, so it may help treat severe cases of COVID-19." (PMID 38606261, 2024). "Herein, targeting STAT3 in COVID-19 may mitigate hyperinflammation and related fatal complications." (PMID 37796433, 2023). "Similarly, the STAT3 pathway, which is involved in the pathogenesis of SARS‐CoV‐2 infection, is stimulated in Covid‐19 by proinflammatory cytokines." (PMID 36444620, 2022). "The STAT3 pathway in myeloid cells is relevant for acquiring immunosuppressive functions and for driving the production of cytokines during immune disorders, two conditions jointly cooperating to establish a severe lymphopenia, one of the signs of clinical severity in COVID-19 patients." (PMID 34518653, 2022). "Since STAT3 is a pro-inflammatory mediator, STAT3 inhibition by SBT-100 may also decrease some of the inflammatory complications associated with checkpoint inhibitor therapy such as pneumonitis and severe COVID-19 pathology." (PMID 35886918, 2022). "For example, TREM1 Signalling (z-score = 3.157; BH p-value = 3.162 × 10–02), STAT3 Pathway (z-score = 0.949; BH p-value = 7.762 × 10–03) and IL-22 signalling (z-score = 1.732; BH p-value = 2.239 × 10–02) were all amongst the pathways upregulated in severe COVID-19 compared to mild COVID-19." (PMID 35844004, 2022). "Furthermore, STAT3 targeting reduced the plasma concentration of several pro-inflammatory cytokines, which are produced at abnormal levels in untreated vFLIP mice and are also a feature of COVID-19." (PMID 34518653, 2022). "High levels of STAT3 phosphorylation was associated with decreased markers of myeloid cell maturation/activation and decreased ex-vivo T cell IFN-gamma production, demonstrating that during COVID-19 dysregulated cellular activation is associated with suppression of immune effector cell function." (PMID 33619472, 2021). "Notably, we found that isorhapontigenin could also target STAT3, suggesting an alternative mechanism of isorhapontigenin on COVID-19." (PMID 34539756, 2021). "The aberrant transcription in the direction of STAT3 may lead to the catastrophic cascades specific for COVID-19 patho-physiologies such as rapid coagulopathy/thrombosis, proinflammatory conditions, profibrotic status, and T cell lymphopenia in infected patients." (PMID 33379366, 2020). "Like AT2 cells, AT1 cells in COVID-19 patients had a PDLIM2 repression-dependent hyper-activation of NF-κB and STAT3." (PMID 41000764, 2025). "Despite their different effects on COVID-19 prognosis and their use of distinct receptor complexes, in cells, both type I and type III IFNs induce activation of STAT1, STAT2, and STAT3, as well as a similar subset of IFN-responsive genes." (PMID 40980495, 2025). "Same as myeloid cells, T cells in COVID-19 patients expressed PDLIM2 at a much lower level and had high NF-κB and STAT3 activation." (PMID 41000764, 2025). "Furthermore, their co-expression with STAT3 and α-SMA, two critical factors implicated in inflammation and fibrosis induction, underscores their potential involvement in exacerbating cardiovascular, pulmonary and common symptoms and complications associated with COVID-19." (PMID 38849961, 2024). "IL-6, an important player in COVID-19, binds IL-6R and gp130 receptors to activate JAK/STAT-3 pathway and then contributes to the CRS observed in COVID-19 and possibly in Long COVID patients." (PMID 36947108, 2023). "Thus STAT-3 may be considered as a possible therapeutic target for severe COVID-19." (PMID 37495990, 2023).
COVID-19 (continued). "Analysis of the transcription factors using the TRRUST database from our data (212 DEGs from GSE36854 and GSE21001) for MPXV infection and COVID-19 database by Metascape identified JUN, REL, STAT3, NFKB1, RELA, SP1, and so on." (PMID 37006463, 2023). "Thus, STAT3 ND inhibitors may be useful for therapy of COVID-19." (PMID 37182134, 2023). "The severity of COVID-19 is related to JAK1-STAT1 dysregulation and compensatory hyperactivation of STAT3." (PMID 37021053, 2023). "Phospho-STAT3 levels in CD4 and CD8 T cells distinguished between healthy donors, moderate COVID-19, and severe COVID-19." (PMID 35421120, 2022). "Most importantly, IL-6 is a vital STAT-3 activator during inflammation, and the IL-6-STAT3 axis has been identified as a critical target for treating COVID-19-induced cytokine storm." (PMID 35563697, 2022). "Here, we reported the mRNA upregulation of STAT3 together with its well-known downstream effectors c-FOS and c-JUN in COVID-19 patients compared with healthy controls." (PMID 35327634, 2022). "Using Venn diagram mapping, we further identified five core ferulic acid targets against OS and COVID-19 via autophagy, including MAPK1, TLR4, PIK3R1, STAT3, and PARP1." (PMID 36204096, 2022). "Among the enriched significant pathways, the Coronavirus disease-COVID-19-related pathways is the most significant pathway which involved most of the hHub-DEGs notably, CXCL8, EGFR, IL6, JUN, MAPK1, STAT3, TNF, and UBA52." (PMID 36016137, 2022). "In alignment with the findings in this study, the aberrant STAT pathway was found to be central to COVID-19, and the acute lung injury also activated EGFR, leading to the phosphorylation of STAT3." (PMID 36499711, 2022). "According to the results of cytoscape, the targets of JFBDS for treating COVID-19 mainly contained EGFR, PIK3CA, lymphocyte-specific protein tyrosine kinase (LCK), mitogen-activated protein kinase 1 (MAPK1), MAPK3, MAPK8, STAT3, TNF, IL2 and RELA." (PMID 35165507, 2022). "From 11 healthy cell-type TRNs and 8 COVID-19 cell-type TRNs, we identified 8 unique central TFs, FOXP1, RUNX1, FOS, SMAD3, JUN, NFKB1, PPARG, and STAT3." (PMID 35458567, 2022). "To confirm the immunomodulatory capacity of STAT3 inhibitors, we tested the ability of these two compounds to control the immunosuppressive functions of c-FLIP-expressing monocytes isolated from COVID-19 patients." (PMID 34518653, 2022). "Based on the 39 core common genes, immune system, cytokine/inflammatory response, signaling by interleukins, TNF-α signaling via NF-kB, IL-6/JAK/STAT3 signaling, TLR signaling, and AGE-RAGE signaling pathways, etc., are found as links between CVD and COVID-19." (PMID 34067609, 2021). "In turn, STAT3 and PAI-1 augmented thrombosis and coagulopathy in COVID-19 possibly by effectively suppressing urokinase-type Plasminogen Activator (uPA) and tissue-type Plasminogen Activator (tPA)." (PMID 34912345, 2021). "In case of CVD + Cancer + CDK + COVID-19, the drugs and targets were lapatinib, gefitinib for EGFR, prednisolone for IL6, and AZD-1480, currently in a phase I/II trial for STAT3." (PMID 34067609, 2021). "Next, we measured the individual phosphorylation of STAT3, STAT1, JNK, p38, and IRF3 proteins and found them all to be increased in COVID-19 neutrophil whole cell lysates; however, it should be noted that the total levels of these proteins were not evaluated." (PMID 33003471, 2020). "As a result, in COVID-19, EGFR signalling may develop into a different pathway that stimulates STAT3 when lung damage occurs, and SARS-CoV-2 infection significantly reduces IFN-I production." (PMID 38628843, 2024). "Moreover, STAT3 and α-SMA expression levels were remarkedly increased at both transcript and protein levels in patients with COVID-19 compared to healthy subjects and were correlated with Three lncRNAs." (PMID 38849961, 2024).
COVID-19 (continued). "Per our search, we found one study available on HIV/COVID-19 signalling pathway that investigated STAT3 but did not look at other STAT pathways, and therefore creates a gap that needs to be researched." (PMID 38628843, 2024). "On the other hand, the inflammatory NOTCH2-IL24 interaction which induces STAT1 and STAT3 to regulate cell proliferation and survival and the inhibitory interactions CTLA4-CD86 and HAVCR2-LGALS9 were unique to patients with COVID-19." (PMID 36992700, 2023). "In this study, Phaseol, Glycyrol and Glyasperin F in licorice may treat COVID-19 to reduce the inflammatory response and promote cell survival by acting on CXCL8, IL2RA, STAT3, and MMP1." (PMID 36120307, 2022). "In contrast, many TFs were identified specifically as the top TFs in COVID-19 patients’ lung cell types, including SMAD3 in ciliated cells, NFKB1 and JUN in dendritic cells, PPARG in macrophage/monocyte cells, and STAT3 in T cells." (PMID 35458567, 2022). "Therefore, we inferred that TP lipo is a multitarget-directed drug for COVID-19 treatment that regulates the NF-κB, p38 MAPK, and STAT3 pathways." (PMID 36566328, 2022). "Notably in both populations, STAT3 phosphorylation predominated, with a >7-fold increase in phospho-STAT3 in CD4 T cells and a >3-fold increase in CD8 T cells in severe COVID-19 subjects vs. healthy donors." (PMID 35421120, 2022). "We identified a significant direct correlation between pSTAT3 and c-FLIP expression in circulating CD14+ cells isolated from COVID-19 patients, hinting to the aberrant activation of FLIP/STAT3 axis in myeloid cells not only at pulmonary site but also in periphery." (PMID 34518653, 2022). "The activation of the STAT3 pathway was recently detected in the kidneys of COVID-19 patients, but viral or virus-like particles were not detectable, further underlining that cytokines and chemokines are released in absence of the triggering agent." (PMID 35336843, 2022). "Considering the dual inhibitory effect of CIB-6 on STAT3 and ACE, CIB-6 could be further explored for development as a new anti-COVID-19 drug." (PMID 33805945, 2021). "Pharmacological correction of STAT3 over-stimulation, which is at the root of acute respiratory distress syndrome (ARDS) and coagulopathy/thrombosis events, should be considered for treatment of severe COVID-19." (PMID 35056076, 2021). "As nearly 80% of patients with COVID-19 appear to eradicate the SARS-CoV-2 virus via antiviral immune responses (e.g., IFN-α/β), JAK/STAT3 inhibitors may be a better approach when hospital care is needed for COVID-19 patients." (PMID 32517353, 2020). "The clinical symptoms of COVID-19 relate to several cytokines including interleukin (IL)-2, IL-7, IL-10, tumor necrosis factor (TNF) with IL-6, IL-6-signal transducer and activator of transcription 3 (STAT3) and nuclear factor kappa B (NF-κB) pathway being of high significance." (PMID 36987476, 2023). "This patient did not experience severe inflammation at the time of COVID-19, but our data nevertheless highlight an enhancement of inflammatory cascades (TNF/NF-κB and IL-6/JAK/STAT3) in STAT2 deficiency, both in the basal state and during acute COVID-19, mediated predominantly by neutrophils." (PMID 36976641, 2023). "Therefore, it is reasonable to speculate that acacetin, wogonin, and isorhamnetin are the main ingredients of JFBDS that treat COVID-19 by regulating PI3K/AKT, STAT3, MAPK, and NF-κB signaling pathways." (PMID 35165507, 2022). "Therefore, the active small molecules Phaseol, Glycyrol and Glyasperin F in licorice may act on CXCL8, IL2RA, STAT3, and MMP1 to treat COVID-19 by reducing tissue damage and inflammatory response." (PMID 36120307, 2022). "The ability of IL-33 to activate both the IL-33/p38/GATA3 and IL-33/MAPK/STAT3 pathways suggests that IL-33 plays a key role in the regulation of ILC2 in pulmonary inflammation, which provides a new perspective for research into the mechanism of the secondary pulmonary symptoms of COVID-19." (PMID 36362440, 2022).